RNU6-391P (RNA, U6 small nuclear 391, pseudogene)
Gene: Small nuclear RNA gene on chromosome 6 (24,365,651 to 24,365,754, forward strand). Ensembl gene ENSG00000202050.
Homologues: Orthologues: chimpanzee U6 (97% identical), macaque U6 (97% identical), pig U6 (80% identical), guinea pig U6 (78% identical), rat U6 (70% identical), dog U6 (64% identical). Paralogues in human: RNU6-393P (88% identical), RNU6-1060P (87% identical), RNU6-1145P (86% identical), RNU6-348P (86% identical), RNU6-41P (86% identical), RNU6-536P (86% identical), RNU6-1075P (85% identical), RNU6-1083P (85% identical), RNU6-116P (85% identical), RNU6-1316P (85% identical), RNU6-140P (85% identical), RNU6-16P (85% identical), and 1286 more.